MTOR (mechanistic target of rapamycin kinase)
Diseases named in the same sentence as MTOR in open-access papers (continued):
Sharing a sentence is not in itself a finding about the gene and the disease.
tumor (continued). "Inhibition of the mTOR pathway may result in the induction of the apoptosis of tumor cells." (PMID 37513979, 2023). "Simultaneous inhibition of glycolysis and oxidative phosphorylation, as well as PI3K/AKT/mTOR and other pathways and involved molecules with dual inhibitors, showed that this strategy is effective in most cases and helps to prevent the growth and development of the tumor." (PMID 37046703, 2023). "There are also no mutations in tumor driver genes and mTOR pathway genes specific to TSC patients." (PMID 37232723, 2023). "However, it was shown that mTOR inhibition could diminish anti-tumor immunity as these inhibitors directly affect the lineage differentiation-determining glycolytic activity in T-cells." (PMID 36768924, 2023). "Additionally, while speculating whether oxidative stress-induced inactivation of PI3K/AKT/mTOR pathway has led to apoptosis, the triple-drug combination triggered the percentage of apoptotic cells when compared with the tumor-control group." (PMID 37025487, 2023). "Our analysis suggests that expression/activation of CDK4/6 substrates in tumor cells and genomic-independent activation of the AKT/mTOR pro-survival signaling pathway in tumor and surrounding stroma/immune cells may predict response to CDK4/6 inhibition in combination with ET in MBC." (PMID 36797347, 2023). "Therefore, mTOR inhibitors have the potential to reduce tumor growth." (PMID 37221626, 2023). "Thus, in our MYC-driven cell models OTX-015 treatment may upregulate myo-inositol production, counteracting PI3K/Akt/mTOR signalling and eventually triggering tumour cell death." (PMID 36690651, 2023). "Therefore, some compounds secreted by tumor cells or the low IGF1 level measured could have downregulated the Akt/mTOR pathway, leading to a decrease in protein synthesis." (PMID 36980729, 2023). "In addition, the AMPK/mTOR signalling pathway has been extensively investigated and reported in a series of diseases because it plays a crucial role in the regulation of autophagy, especially in tumour progression." (PMID 37801481, 2023). "In HCC, the EGFR/PI3K/AKT/mTOR pathway is abnormally activated in approximately 50% of cases, and this dysregulated activation is involved in various cellular processes, including cell proliferation, tumor cell differentiation, autophagy, metabolism, and the epithelial–mesenchymal transition (EMT)." (PMID 37631344, 2023). "PI3K/AKT/mTOR pathway inhibitors (i.e. rapamycin, everolimus) are well-known autophagy inductors and their combination with other cytotoxic molecules could enhance antitumor efficacy and restrict repopulation of tumor cells between cycles of cytotoxic drugs." (PMID 36871010, 2023). "Therefore, both mTORC1 and mTORC2 functions provide an important rationale for targeting mTOR complexes in tumor, although the effectiveness of some mTORC inhibitors may be compromised by a compensatory feedback loop leading to AKT activation." (PMID 37596643, 2023). "This indicated that the interaction between ZNRF2 and mTOR may be involved in tumour growth." (PMID 37551845, 2023). "Therefore, the effect of LNT on p62/mTOR, NF‐κB signaling pathway, and autophagic cell death on tumor cells stimulated by TNF‐α could also depend on Nur77." (PMID 37249285, 2023). "However, in some RCC subtypes, somatic alterations in mTOR pathway genes occur in a background of classic mutations associated with the respective RCC subtype, and may drive tumor progression." (PMID 37627070, 2023). "AMPK is an important link in the metabolic and signaling networks that acts as a metabolic tumor suppressor by influencing energy levels, implementing metabolic checkpoints, inhibiting cell growth, and downregulating the mammalian target of rapamycin (mTOR) pathway." (PMID 36850263, 2023).
tumor (continued). "Novel non-selective inhibitors of mTOR are currently under preclinical and clinical developments in oncology, attempting to overcome some limitations associated with selective inhibitors, such as the development of tumor resistance." (PMID 37372982, 2023). "If the global activation of the PI3K/AKT/mTOR signaling axis in the tumor epithelium and stroma compartment is validated in independent cohorts of samples, this assay may provide clinically useful information even from whole tissue samples without requiring additional cellular enrichment steps." (PMID 36797347, 2023). "In addition, tumour cells are likely to be able to induce pathological changes in interneurons or pyramidal cells, induce hyperexcitability and trigger epileptogenesis by acting through the mTOR pathway." (PMID 38067243, 2023). "Additionally, we constructed a stable cell line with TSC2 knockdown, which is the classical model that leads to constitutively active mTOR, and found that the tumor suppressive effect of VC could be eliminated by the knockdown of TSC2." (PMID 36787291, 2023). "In the present study, the PLD1 was significantly downregulated in the cold season, which could effectively reduce the PA content in lipid metabolism, thereby inhibiting tumor cell genesis and proliferation through the Akt/mTOR signaling pathway and Wnt signaling pathway." (PMID 37833936, 2023). "Additionally, mTOR activation develops radiation and chemotherapy resistance, enhances DNA repair, promotes survival, and supports GSCs while fostering an immunosuppressive tumor microenvironment for immune evasion." (PMID 37834408, 2023). "Additionally, selective GLUT-1 inhibitors such as rapamycin (mTOR-signaling inhibitor), metformin, and a ketogenic diet may reduce tumor glucose uptake and thereby improve CAR T-cell metabolism in the TME." (PMID 37020537, 2023). "Intriguingly, the suppression of mTOR activity is known to enhance the efficacy of dasatinib in other tumor types, and it may be worth investigating in the future whether this enhanced efficacy is the result of mTOR’s metabolic regulation or the metabolic changes are indicative of mTOR activity." (PMID 37408209, 2023). "Therapy resistance to mTOR inhibition may be due to a metabolic adaptation in the tumor cells." (PMID 37298093, 2023). "In conclusion, we showed that C-VGB3, which reproduces a binding region of VEGFB, could interfere with the interaction between VEGFA and VEGFR2 and inhibit angiogenesis and tumor growth via suppression of PI3K/AKT/mTOR and PLCγ/ERK1/2 pathways in both endothelial and tumor cells." (PMID 37375853, 2023). "Moreover, inhibiting PI3K/AKT/mTOR can promote the secretion of immunosuppressive cytokines and infiltration of myeloid-derived suppressor cells (MDSCs), which would enhance the anti-tumor immune response." (PMID 36960074, 2023). "Therefore, we hypothesized that ZNRF2 mediates the regulatory network of the mTOR signalling pathway and thus might influence the molecular mechanisms of tumour development." (PMID 37551845, 2023). "Therefore, we hypothesized that mTOR expression might be employed as a biological marker for tumor invasion and metastasis in addition to OS diagnosis." (PMID 37441462, 2023). "Consequently, the relationship between PIK3C2A, ubiquitin, insulin, and the mTOR signaling pathway may be an important modulator of tumor immunity." (PMID 37063922, 2023). "Furthermore, miRs can regulate tumor resistance in NSCLC by targeting the PI3K/AKT/mTOR pathway." (PMID 37901797, 2023). "Genetic inactivation of autophagy in tumor cells can also enhance the efficacy of immune checkpoint inhibitors in mouse tumor models, in which autophagy is activated in tumor cells by inhibiting mTOR signaling; this promotes tumor cell escape from T cell-mediated killing." (PMID 37006252, 2023). "Moreover, aspirin could activate AMPK, inhibit mTOR to induce autophagic cell death, and suppress tumor development." (PMID 37190124, 2023).
tumor (continued). "This study expands on previous research to further explore the role of metabolic regulation mechanism in the immunosuppressive microenvironment of OC cells and to try to investigate whether TLR8/mTOR signal may be a potential target for tumor immunotherapy in the future." (PMID 37317670, 2023). "Although direct evidence linking HOTAIR to autophagy in the tumour promoting and drug resistance effects of CML is currently lacking, it is worth exploring the relationship between HOTAIR and autophagy considering the close association between the PI3K/AKT/mTOR pathway and apoptosis with autophagy." (PMID 37837401, 2023). "Additionally, studies suggest that glutaminase and mTOR inhibition causes GBM cell death and tumor inhibition in a xenograft model, resulting in an increased intracellular glutamate level and upregulation of glutaminase in GBM U87MG, and to a greater extent in U87/EGFRvIII cells." (PMID 36831355, 2023). "Therefore, the block of both MEK and PI3K/AKT/mTOR pathways with a combination of different signalling inhibitors may be used to more effectively target tumor cells, as compared with treatment with a single agent." (PMID 36765661, 2023). "By regulating mTOR activity, translation, and autophagy, glutamine also coordinates the proliferation and growth of tumor stem cells, which could explain why the -GFs, Gln medium variant was observed here to be stronger than the medium without the GFs proliferation rate inhibition only." (PMID 36766833, 2023). "Therefore, mTOR can be a good entry point for tumor treatment." (PMID 36849137, 2023). "Therefore, SHR-5 may inhibit the PI3K/mTOR signaling leading to the reduction in CoA in tumor tissues." (PMID 37370698, 2023). "Moreover, PD-L1 expressed in TCs may activate antiapoptotic signals, enhancing the PI3K–Akt-mTOR pathway and tumor-intrinsic glycolysis." (PMID 37190322, 2023). "Through GSVA and GSEA, we observed a significant activation of tumor-associated biological processes such as EMT, cell proliferation (MYC targets, E2F targets, G2M checkpoints, and cell cycle), and signaling pathways like WNT/β-catenin and PI3K/AKT/MTOR pathways in the high PCDI score group." (PMID 38170006, 2023). "Therefore, the inhibition of both PI3K and mTOR may enhance anti-tumor activity compared to the mTOR-block alone." (PMID 36765661, 2023). "However, the role of mTOR in the regulation of stemness is not fully understood, and additional studies are required to confirm these findings, considering that mTOR inhibition may have a long-term beneficial effect on reducing tumor recurrence." (PMID 36792625, 2023). "Our results showed that CTSG down-regulated expression effects on tumor growth might be reversed, and Akt phosphorylation level and its downstream substrate mTOR decreased after using MK2206, indicating that CTSG may suppress CRC growth through Akt/mTOR signaling pathway." (PMID 37151875, 2023). "Among seven potential tumor-suppressing miRNAs identified in this study, high expression of miR-100 was associated with better outcomes in women with luminal A tumors treated with adjuvant endocrine therapy and was inversely linked to mRNA expression of PLK1, FOXA1, mTOR, and IGF1R." (PMID 37508580, 2023). "Increasing evidence suggests that numerous m6A targets contribute to tumorigenesis, including Snail, CTNNB1, NANOG, APC, and genes associated with the Akt/mTOR pathway However, conflicting reports have indicated that METTL3 may function as a tumor suppressor in certain tumor types." (PMID 38012755, 2023). "Since pro-inflammatory cytokines, reactive oxygen, and nitrogen species (RONS) activate Akt/PI3K/mTOR signaling and stimulate oncogenesis and tumor progression in BC, the MIND diet might suppress these mechanisms through its antioxidant and anti-inflammatory properties." (PMID 36303232, 2022).
tumor (continued). "Interestingly, the PI3K/AKT/mTOR pathway mediates signaling from leptin and IL-6, which, in our study, have been found to be significantly elevated in type I endometrial cancer patients and positively correlated with tumor prognostic factors." (PMID 35053431, 2022). "However, a recent study puts mTOR pathway in a different light, highlighting how it may indirectly reinforce the lymphocytic response against tumor cells, eventually contributing to CDK-i efficacy." (PMID 35712501, 2022). "Thus, besides its tumor-targeted mode of action, mTOR inhibition may also affect the antitumor immune response within the TME." (PMID 36139669, 2022). "Moreover, virus-mediated overexpression of miR-199 and miR-34a has been found to lead to control of tumor growth by targeting mTOR, c-MET, HIF-1α, and CD44, as well as complete tumor regression by targeting Bcl-2 and SIRT1 in xenograft murine models of HCC, respectively." (PMID 35954176, 2022). "In addition, FJD could significantly downregulate the protein levels of p-PI3K/PI3K, p-AKT/AKT, p-mTOR/mTOR, NF-κB, p38, and Bcl-2 and upregulate the Bax, Cyt-C, and cleaved caspase-3 in OC tumor tissues and cells." (PMID 35281608, 2022). "Therefore, targeting mTOR has great potential in tumor therapy." (PMID 35874739, 2022). "Moreover, other pathways are also involved in this tumor progression such as PI3K/AKT/mTOR pathway activation in 30–40% of patients, DDR gene alterations in 20–30% of patients, cell cycle alterations in 20% of patients, or the Wnt signaling pathway in 18% of patients." (PMID 36551557, 2022). "Interestingly, previous studies suggested that targeting PI3K/AKT/mTOR signalling could inhibit tumour progression by augmenting tumour immunosurveillance, preventing activation of immunosuppressive signalling and activating anti-tumour immunity." (PMID 35043008, 2022). "Particularly, the tumor suppressor gene PTEN negatively regulates the PI3K/AKT/mTOR pathway, therefore, PTEN deficient tumors could potentially benefit from inhibiting AKT or mTOR." (PMID 35881043, 2022). "Taken together, these data indicated that the combination of ATO/PTL endows the HCC cell lines with much stronger autophagic activity than each reagent via inhibiting the PI3K/Akt/mTOR pathway, which may weaken the anti-tumor efficacy of the combination of PTL and ATO." (PMID 36353537, 2022). "Moreover, since mTOR not only improves cell proliferation, growth, and survival but also drives the tumour cell motility and invasiveness, the observed expression alterations may explain the higher migration levels of treated HEK293T than hTERT-HPNE cells." (PMID 36289850, 2022). "Moreover, HIF-1α may play a central role in tumorigenesis by upregulating different signaling pathways such as Myc and PI3K/AKT/mTOR that are involved in tumor proliferation, differentiation, migration, and invasion." (PMID 35845307, 2022). "Furthermore, CWR22 xenografts treated with a combination of PI3K/mTOR inhibitor and either Riluzole (blocking agent for glutamate release) or lapatinib showed significant reduction in tumor volume after a 2-week treatment, when compared with their single-agent controls." (PMID 35086953, 2022). "In xenotransplanted NSCLC nude mice derived from A549 cells, TBs-C could significantly suppress tumor growth by inhibiting the PI3K/AKT/mTOR pathway without causing hepatotoxicity, brain toxicity, or nephrotoxicity." (PMID 35529455, 2022). "Therefore, targeting AMPK/mTOR can effectively inhibit tumor formation and enhance chemotherapeutic sensitivity, and disruption of ATP level may be a more straightforward strategy to overcome drug resistance." (PMID 36293209, 2022). "The autophagy in PCa induced by CHRM1 was summarized with a model, which activates the AMPK/mTOR pathway by linking the Gq protein, acts on Atg5 and other autophagy-related genes, and induces autophagy, thereby enhancing the migration and invasion ability of tumor cells." (PMID 35720225, 2022).
tumor (continued). "Furthermore, the inhibition of the mTOR signaling pathway would result in a lower production of growth factors and inflammatory cytokines involved in tumor progression; in these patients, the antitumor effect of everolimus could be more marked." (PMID 35805003, 2022). "However, recent studies have found that mTOR signaling pathway may be closely related to the methylation of m6A in regulating tumor metabolism." (PMID 35022030, 2022). "For instance, DEGs associated with the ECM-receptor interaction pathway (also involved in PI3K/Akt/mTOR activation) were predominantly upregulated (~ 80%) in LB fHER2− tumours, and represented a combination of approximately half up- and downregulated DEGs in TN tumours." (PMID 36220861, 2022). "Therefore, miRNAs not only promote but also inhibit PI3K/AKT/mTOR-mediated autophagy in tumours." (PMID 35883139, 2022). "Therefore, poor prognosis patients with low ALOX12B expression had high infiltration of CAFs surrounding tumor cells, and rapamycin or everolimus may provide survival benefits by inhibiting mTOR signaling." (PMID 35768785, 2022). "Thus, PI3K/Akt/mTOR pathway activation may be critically involved in CXCR4-mediated promotion of tumor aggressiveness in EOC." (PMID 35681259, 2022). "Moreover, a correlation between tumor progression markers (mTOR) and the BMI was observed." (PMID 35574343, 2022). "Therefore, the combination of the mTOR inhibitor and therapeutic antibody against PD-L1 might improve the anti-tumor efficacy." (PMID 35402280, 2022). "Therefore, because patient MA01 tumor organoids were responsive to both crizotinib and the mTOR inhibitor, everolimus, the treatment of the patient with a combination of these drugs might have been clinically effective." (PMID 35743016, 2022). "PI3K/AKT/mTOR pathway is frequently activated in TNBC, through gain of function mutation of PI3KCA and of loss of function of PTEN, and, therefore, the pharmacological inhibition of PI3K/AKT pathway can, in theory, represent a successful treatment strategy in these tumours." (PMID 35761360, 2022). "However, tumor tissue editing in refractory systems states prompted a novel therapy quality of mTOR inhibitors, here everolimus or temsirolimus, respectively, which could not be achieved with the tissue reprogramming therapy alone (unpublished data)." (PMID 35814409, 2022). "Consequently, the tumor growth suppression may attribute at least partly to the dysfunction of mTOR network." (PMID 36147460, 2022). "mTOR deregulated status in canine carcinogenesis could be related with other several molecules with multidirectional functions, compromising the value of this protein as a biomarker of prognosis in these tumours." (PMID 35883491, 2022). "The “RAS/MAPK signaling pathway” and “RTK signaling pathway” can promote the growth and proliferation of tumor cells, while the “TSC/mTOR signaling pathway” can promote tumor angiogenesis, which may be another mechanism by which APOBEC1 plays a carcinogenic role." (PMID 36339709, 2022). "Indeed, our finding is in accordance with a recent study showing that the overexpression of SIRT1 in liver tumoral cells contributes to the accumulation of p62 and activation of mTOR, thus inhibiting autophagy and contributing to tumor progression and poor prognosis in patients." (PMID 34952202, 2022). "Therefore, the overexpressed DEPTOR may inhibit the mTOR signaling pathway and thus exerted a tumor suppressor effect." (PMID 35507914, 2022).